MGMT (O-6-methylguanine-DNA methyltransferase)
Diseases named in the same sentence as MGMT in open-access papers (continued):
Sharing a sentence is not in itself a finding about the gene and the disease.
breast carcinoma (continued). "The western blotting, qRT-PCR, proliferation, colony formation and transwell assays were used to investigate the potential function of MGMT in breast cancer cells." (PMID 33033516, 2020). "This study is intended to elucidate the prognostic significance and potential function of MGMT in breast cancer." (PMID 33033516, 2020). "The positive rate of MGMT in ER+ breast cancer tissues (32%) was significantly higher than in ER- counterparts (20%)." (PMID 33033516, 2020). "Until recently, reports on the expression and potential role of MGMT in breast cancer remain controversial." (PMID 33033516, 2020). "Future studies on the specific role of MGMT in the pathogenesis and development of breast cancer, particularly in ER-positive subtype, are warranted." (PMID 33033516, 2020). "Next, transwell assays were conducted to evaluate the impact of MGMT on the migratory capacity of breast cancer cells." (PMID 33033516, 2020). "In this study we also show that BG induced MGMT inhibition sensitizes ER positive MCF7 breast cancer cells to TMZ." (PMID 30038716, 2018). "Inhibition of MGMT by TMZ is associated with induction of cytochrome c and p21 expressions in breast cancer cells." (PMID 30038716, 2018). "Here, we evaluate MGMT’s role in control of other clinically relevant targets involved in cell cycle regulation during breast cancer oncogenesis." (PMID 30038716, 2018). "The DNA damage repair enzyme, O6-methylguanine DNA methyltransferase (MGMT) is overexpressed in breast cancer, correlating directly with estrogen receptor (ER) expression and function." (PMID 30038716, 2018). "We also show that MGMT inhibition increases ER positive breast cancer sensitivity to alkylator based chemotherapy." (PMID 30038716, 2018). "Temozolomide in combination with whole brain radiation did not significantly improve local control and survival in patients with brain metastases due to breast cancer underscoring the role of MGMT over expression in metastatic breast cancer." (PMID 30038716, 2018). "Results of this small study hint at the importance of MGMT status when targeting breast cancer with alkylator based combinations." (PMID 30038716, 2018). "In this study we evaluate the potential MGMT’s role in control of therapeutic, clinically relevant, cell cycle regulators involved in breast cancer oncogenesis (CDC2, TOP2A, AURKB, CDC20, KIF20A, Cyclin A2, Cyclin B2, Cyclin D1)." (PMID 30038716, 2018). "Others have already reported in an ER positive breast cancer xenograft model the benefit of lomeguatrib (an oral MGMT inhibitor) in restoring temozolomide sensitivity." (PMID 30038716, 2018). "These genes include BRCA1 in breast cancer, MGMT in gliobastoma multiform (GBM), and MLH1 in colon cancer." (PMID 29038612, 2017). "This occurs through somatically acquired inactivation of the MGMT gene in various cancer types, including breast cancers." (PMID 28679371, 2017). "Of these, DNA repair of alkylation damage by direct reversal has been suggested following the identification of CpG promoter methylation of the MGMT gene in breast cancer." (PMID 28679371, 2017). "The MGMT promoter has been found to be methylated heterogeneously in patients with breast cancer, in diffuse large B-cell lymphoma and in human breast cancer cell line HS578T." (PMID 26370119, 2015). "Taken together, the ERp29-induced MGMT is a key molecule promoting ERp29-mediated radioresistance in breast cancer cells." (PMID 26420420, 2015). "Of these, MGMT positivity was identified in 398 (63%) of 635 breast cancers; 68% of luminal A, 67% of luminal B, 30% of HER2+/ER− and 46% of basal-like subtypes were positive." (PMID 24932232, 2014). "The correlation between MGMT expression and prognosis in the subtypes of breast cancer, managed according to common therapeutic protocols, was then investigated." (PMID 24932232, 2014).
breast carcinoma (continued). "A recent study indicated that the MGMT promoter methylation status predicts tumor response to alkylating drugs in patients with triple-negative (TN) breast cancer." (PMID 24932232, 2014). "The intrinsic subtypes and MGMT protein expression levels were assessed in 635 consecutive patients with breast cancer using immunohistochemistry." (PMID 24932232, 2014). "In the present study, immunohistochemical analyses of breast tumor subtypes and MGMT protein expression were conducted using formalin-fixed, paraffin-embedded specimens obtained from patients with breast cancer." (PMID 24932232, 2014). "Next, MGMT protein expression as a possible prognostic factor in breast cancer subtypes was examined using the Kaplan-Meier method." (PMID 24932232, 2014). "When analyzing the clinical outcomes of these patients, no recurrence was observed in those with MGMT-negative tumors, however, 4 of the 6 patients with MGMT-positive tumors had breast cancer recurrences." (PMID 24932232, 2014). "Meanwhile, epigenetic silencing caused by methylation was previously observed for at least five ASE genes identified in our study, including DSC3, FGFR2 and MGMT in breast cancer and/or in other cancer types." (PMID 21108794, 2010). "Notably, the CF methylation carriers expressed significantly higher levels of the two genes (p = 0.0001 for BRCA1 and 0.015 for MGMT) than the breast cancer patients." (PMID 38542081, 2024). "Finally, our new data show that the amounts of BRCA1 and MGMT mRNA in WBC RNA are much higher in patients with breast cancer and CF epimutation carriers compared to the control group." (PMID 38542081, 2024). "Similarly, the ratio of MGMT promoter methylation was significantly higher in a sample of Chinese breast cancer patients compared with controls." (PMID 33883026, 2021). "Future study on targeted modulation of MGMT in the treatment of breast cancer is warranted." (PMID 33033516, 2020). "However, reports on the protein expression profiles and prognostic significance of MGMT in breast cancer remain inconsistent." (PMID 33033516, 2020). "MGMT negativity resulting from methylation of MGMT may contribute to alkylating agent sensitivity in breast cancer, thereby leading to a longer DFS for patients receiving postoperative adjuvant chemotherapy." (PMID 33033516, 2020). "Notably, the mother of a BRCA1 woman carrier was a breast cancer patient who was positive for methylated MGMT." (PMID 30049288, 2018). "MGMT inhibition in our model led to significant decrease in the multiple cell cycle regulatory targets tested suggesting that MGMT inhibition could be considered as an adjunct to distant inhibition of these multiple targets in the treatment of breast cancer." (PMID 30038716, 2018). "In breast cancer, MGMT has been reported to control ER expression and function." (PMID 30038716, 2018). "In breast cancer, MGMT and ER are largely expressed along a quantitative and qualitative continuum." (PMID 30038716, 2018). "This study is aimed to evaluate expression and transcription correlations between MGMT and already clinically relevant cell cycle regulators involved in breast cancer oncogenesis, chemotherapy resistance (TOP2A for anthracyclines, KIF20A for taxol) and hormonal therapy resistance (ARUKB)." (PMID 30038716, 2018). "TMZ is a weak alkylator taking 4-6 days to inhibit MGMT in breast cancer cells." (PMID 30038716, 2018). "Targeting ERp29\MGMT axis may be useful for providing better treatment efficacy in combination with radiotherapy in breast cancer." (PMID 26420420, 2015). "Finally, the present study demonstrated that the MGMT expression level and improvement in clinical outcomes are significantly correlated among patients with basal-like breast cancers who receive CPM-containing adjuvant chemotherapy." (PMID 24932232, 2014). "MGMT positivity was identified in 398 (63%) of 635 patients with breast cancer." (PMID 24932232, 2014).
breast carcinoma (continued). "Taken together, the results of the present study indicate that MGMT protein expression could be a useful prognostic and predictive marker of patients with basal-like breast cancer who are treated with CPM-containing chemotherapy." (PMID 24932232, 2014). "Certain clinical studies have indicated that MGMT expression correlates with the prognosis of breast cancer, whereas other clinical studies have failed to elucidate any association between MGMT expression and OS in patients with breast cancer." (PMID 24932232, 2014). "The present study investigated whether MGMT expression was correlated with prognosis in patients with breast cancer that was managed according to a common therapeutic protocol or treated with CPM-based chemotherapy." (PMID 24932232, 2014). "The MGMT methylated band was detected in WBC of all breast cancer cases and carrier samples." (PMID 25403427, 2014). "In total, 63% of the 635 patients with breast cancer harbored MGMT-positive tumors." (PMID 24932232, 2014). "In breast cancer, non-conserved amino acid changes encoded by MGMT SNPs could significantly increase breast cancer risk." (PMID 39334297, 2024). "A study from Saudi Arabia observed that epimutations on BRCA1 and MGMT genes (both genes have been related to breast cancer) can be transmitted from mothers to female newborns, which could potentially transmit breast cancer risk from mothers to their daughters." (PMID 36966332, 2023). "Even though the research findings of MGMT methylation in breast cancer have been inconsistent, a study showed that methylating the MGMT promoter in chemoresistant TNBC cells results in the re-sensitization to chemotherapy, implying that MGMT could be a feasible target for chemoresistant TNBC." (PMID 34359598, 2021). "However, the role of MGMT in breast cancer was poorly elucidated." (PMID 33033516, 2020). "Moreover, MGMT expression could affect the proliferative and invasive abilities of breast cancer cells through the PTEN/AKT pathways." (PMID 33033516, 2020). "We hypothesized that MGMT can negatively regulate Akt via up-regulation of PTEN in breast cancer." (PMID 33033516, 2020). "Moreover, MGMT could affect the proliferative and invasive capacities of breast cancer cells through regulating the PTEN/AKT pathway." (PMID 33033516, 2020). "The longstanding belief has been that breast tumors are heterogeneous with respect to MGMT expression, however, these contradictory results could be due to the majority of previous studies being evaluated in heterogeneous groups of patients with breast cancer." (PMID 24932232, 2014). "PaTrin-2 is a more potent MGMT inactivator in vitro than O6-BeG, and we considered it worthwhile to examine the extent to which PaTrin-2 could inactivate MGMT and increase sensitivity to temozolomide in a human breast tumour model as a prerequisite for any potential clinical trial in breast cancer." (PMID 16278661, 2005). "Histone modification and DNA methylation of MGMT, BRCA-1, and P16 were assessed in a sample of Iranian breast cancer patients." (PMID 33883026, 2021). "It has been shown that the promoter methylation of MGMT and BRCA-1 were higher in malignant breast tumor (MBT) compared with benign breast tumor (BBT) cases, while the P16 promoter methylation was lower in MBT patients compared with BBT." (PMID 33883026, 2021). "Positive expression of MGMT predicts a longer distant-free survival (DFS) and overall survival (OS) in patients with breast cancer, especially in ER-positive tumor." (PMID 33033516, 2020). "Positive expression of MGMT predicted a better DFS and OS in patients with breast cancer, especially in ER-positive breast cancer." (PMID 33033516, 2020). "We show that O6-benzylguanine (BG), an MGMT inhibitor decreases CDC2, CDC20, TOP2A, AURKB, KIF20A, cyclin B2, A2, D1, ERα and survivin and induces c-PARP and p21 and sensitizes ER positive breast cancer to temozolomide (TMZ)." (PMID 30038716, 2018).
breast carcinoma (continued). "Promoter methylation levels of HIN-1, MGMT and RASSF1A were found to be potential biomarkers for detecting field cancerization in breast cancer patients." (PMID 28403857, 2017). "We chose the breast cancer cell line MCF-7, which is known to have high levels of MGMT (3.24 pmol/mg of protein), and two colon cancer cell lines, HT-29 (1.14 pmol/mg of protein) and SW48 (<0.05 pmol/mg of protein), known to have lower levels of activity." (PMID 27035132, 2016). "CCND2, DAPK1, GSTP1, HIN-1, MGMT and RASSF1A were selected because they have previously been reported to be frequently methylated in primary breast cancers." (PMID 26370119, 2015). "MS-HRM analysis was carried out to determine the methylation status of CCND2, DAPK1, GSTP1, HIN-1, MGMT and RASSF1A promoters in tumor tissues and histologically normal-appearing tumor-adjacent and tumor-distant tissues of 17 breast cancer patients." (PMID 26370119, 2015). "In order to validate the signature PCR Array data, the methylation status of MGMT was analyzed by MSP in five control samples, two breast cancer cases, and two carriers." (PMID 25403427, 2014). "Among the patients with basal-like breast cancer treated with a CPM-containing regimen, those with MGMT-negative tumors had a better DFS rate compared with those with MGMT-positive tumors." (PMID 24932232, 2014). "However, the expression of both genes was greater in the breast cancer patients (p = 0.033 for BRCA1 and 0.049 for MGMT)." (PMID 38542081, 2024). "There were 74 (26.9%) cases with MGMT positive expression and 201 cases (73.1%) with MGMT negative expression in the 275 breast cancer samples." (PMID 33033516, 2020). "Through analysis in bc-GenExMiner v4.0 database, we found that the mRNA level of MGMT in ER positive subgroup were significantly higher than ER negative subgroup of breast carcinoma." (PMID 33033516, 2020). "Further, the BG induced MGMT inhibitory effect enhancing Temozolomide cell viability inhibitory effect extends to a variety of breast cancer cells, irrespective of presence or absence of 17-β estradiol (E2)." (PMID 30038716, 2018). "However, in a cohort of 17 breast cancer patients who were tested positive for BRCA1 methylation in our previous study, four patients (23.5%) were found to be positive for MGMT methylation." (PMID 30049288, 2018). "In a previous study, we determined the promoter methylation status of six tumor suppressor genes (CCND2, DAPK1, GSTP1, HIN-1, MGMT and RASSF1A) in tumor, tumor-adjacent and tumor-distant tissues from breast cancer patients and normal breast tissues from healthy controls." (PMID 28403857, 2017). "During the treatments with veliparib and ponatinib, SNVs occurred on or near LATS1 (a core component of Hippo-YAP pathway), MGMT (related to DNA damage), IL17RB (related to NF-κB signaling) and APCDD1L (related to wnt signaling), all of which are known to be related to breast cancer." (PMID 29208983, 2017). "Methylation-sensitive high-resolution melting was used to screen promoter methylation in a panel of 13 genes reported as methylated in breast cancer (RASSF1A, TWIST1, APC, WIF1, MGMT, MAL, CDH13, RARβ, BRCA1, CDH1, CDKN2A, TP73, and GSTP1) in 29 tumour pairs (16 ipsilateral and 13 contralateral)." (PMID 26452468, 2015). "Breast cancers with no lymph node metastasis were more likely to be MGMT-positive than those with positive lymph nodes." (PMID 24932232, 2014). "MGMT may be a useful prognostic and predictive marker for CPM-containing chemotherapy in basal-like breast cancer." (PMID 24932232, 2014). "It was therefore concluded that MGMT protein expression generally has no prognostic value for breast cancers." (PMID 24932232, 2014). "Similarly, multiple tumor suppressor genes known to be methylated in breast cancer, such as Maspin, CDH1, MGMT, and p21WAF1/Cip1, were downregulated in OTBCs relative to the parental lines." (PMID 21952072, 2011).
breast carcinoma (continued). "Included among the genes epigenetically silenced in breast cancer are genes involved in cell cycle regulation (p16INK4A, CCND2, RASSF1A), cell signaling (SFRP1, SFRP5), differentiation (HOXA9), immortalization (p57), and DNA repair (MGMT, BRCA1)." (PMID 19995452, 2009). "High levels of MGMT expression in the primary tumour have been correlated with a poor prognosis in early breast cancer, irrespective of the treatment regimen." (PMID 16278661, 2005). "We did not detect any case with both BRCA1 and MGMT methylations in breast cancer patients." (PMID 30049288, 2018). "MGMT expression was not significantly correlated with breast cancer subtype." (PMID 24932232, 2014). "However, MGMT expression was not correlated with OS or DFS among the patients with breast cancer in the present study." (PMID 24932232, 2014). "Furthermore, among the patients with basal-like breast cancer with an MGMT-negative phenotype, those who received CPM-containing chemotherapy exhibited an improved DFS rate compared with those who received chemotherapy without CPM." (PMID 24932232, 2014). "However, the clinical outcomes of patients with other subtypes of breast cancer were independent of the MGMT status, irrespective of the treatment with CPM-containing chemotherapy." (PMID 24932232, 2014).